BCL2 (BCL2 apoptosis regulator)
Diseases named in the same sentence as BCL2 in open-access papers (continued):
Sharing a sentence is not in itself a finding about the gene and the disease.
melanoma (continued). "The increased expression of BCL-2 in GCs and follicle wall as observed in the present study is similar to the findings reported in melanoma and neuronal cells." (PMID 21701678, 2011). "One anti-apoptotic agent, Oblimersen, an anti-sense agent targeted at nuclear Bcl-2 has exhibited mixed results in melanoma." (PMID 21479172, 2011). "Numerous studies have demonstrated Bcl-2 over-expression in solid tumors, including melanoma, breast, colorectal, prostate, and small cell lung cancer as well as cancers of hematological origin." (PMID 21304176, 2010). "Currently the antisense oligonucleotide with bcl-2 as the target gene (trade name: Oblimersen) is in Phase III clinical trials with the permit of FDA (mainly treat malignant melanoma, chronic lymphocytic leukemia, multiple myeloma, etc.)." (PMID 20525250, 2010). "In melanoma, it has been described that Bcl-2 expression was significantly higher in the primary tumors as compared to metastatic lesions." (PMID 21304176, 2010). "The BCL2 protein, which inhibits mitochondria-mediated apoptosis, is often overexpressed in melanoma." (PMID 24281185, 2010). "MiTF also controls the expression of Tbx2 and CDK2, which are involved in melanoma proliferation and suppression of senescence, in addition to anti-apoptotic genes such as Bcl2 and ML-IAP." (PMID 20174581, 2010). "In phase II clinical trials of oblimersen in combination with DTIC, BCL2 expression was decreased by 42% in melanoma samples." (PMID 24281185, 2010). "Anti-apoptotic proteins such as Bcl-2 are found in many cancers, including breast, colon, prostate, and lung carcinomas, as well as melanoma." (PMID 24281076, 2010). "A number of studies have reported overexpression of Bcl-2, Mcl-1 and Bcl-xL in melanoma compared to normal tissue or benign nevi, although there is some controversy as to the role of Bcl-2 expression in chemoresistance." (PMID 19684859, 2009). "In melanoma cell lines it was shown that sorafenib treatment can induce cell death, leading to Bad dephosphorylation, decrease in the levels of Bcl-2 and Bax activation." (PMID 19878585, 2009). "Bcl-2 downregulation in melanoma cells after sorafenib treatment occurs in cell lines harbouring BRAF mutation but seems to be ERK-independent." (PMID 19878585, 2009). "For example, several defects in the apoptotic machinery have been reported in melanoma, such as upregulation of bcl-2, or epigenetic silencing of DAP kinase and Apaf-1." (PMID 19367282, 2009). "Although some authors have described an increase in bcl-2 during the progression of normal melanocytes to melanomas, others have observed the opposite." (PMID 18570663, 2008). "Because of the critical role of the mitochondrial pathway in melanoma, approaches targeting anti- and proapoptotic Bcl-2 proteins are of particular interest." (PMID 19506730, 2008). "In particular, resistance to MAPK inhibition based on high levels of antiapoptotic Bcl-2 proteins was overcome in melanoma cells by another small molecule BH3 mimetic (TW-37) developed by computer modeling for binding to Mcl-1, Bcl-xL and Bcl-2." (PMID 19506730, 2008). "It has been shown that the treatment of melanoma cells with oligonucleotides targeting the reduction of bcl-2 expression rendered those cells more sensitive to chemotherapy." (PMID 18570663, 2008). "Bcl-2 proteins, which will be the topic of this review, are major players in the regulation of apoptosis, and melanoma will be used as an example for discussing therapeutic strategies for targeting Bcl-2 proteins." (PMID 19506730, 2008). "Indicative for its critical role, Bcl-2 overexpression reduced basic apoptosis and sensitivity of melanoma cells for proapoptotic stimuli." (PMID 19506730, 2008). "Bcl-2 itself is highly expressed in the majority of cases of acute leukaemia, approximately 50% of diffuse large B-cell lymphomas and up to 90% of malignant melanomas." (PMID 17311012, 2007).
melanoma (continued). "For examples, PI3K/Akt and Erk signaling pathways are involved in bcl-2-induced VEGF expression in melanoma cells." (PMID 18159242, 2007). "While some studies indicated that Bcl-2 and Bcl-XL gene expression increases with progression of malignant melanoma, others found that Bcl-2 and Bcl-XL did not correlate to progression of the disease." (PMID 15305193, 2004). "The localisation pattern of immunostaining has also been shown to have prognostic value with other markers in cancer like bcl-2 expression in malignant melanoma." (PMID 14520458, 2003). "For melanoma, clinical studies using antisense oligonucleotides against the antiapoptotic Bcl-2 are on the way aiming the sensitisation of tumour cells against chemotherapy." (PMID 12085193, 2002). "Another study investigating the methanol extracts of C. patula, C. pulchella, and C. tchihatchheffii on the A375 (human melanoma cell line) revealed a decrease in anti-apoptotic Bcl-2 expression and an increase in pro-apoptotic Bax expression, confirming the pro-apoptotic effects." (PMID 41155672, 2025). "In this study, we aimed to investigate whether LNT regulates the Nur77/Bcl-2 apoptotic pathway to inhibit melanoma growth." (PMID 39744474, 2025). "Activin A neutralization through systemic intravenous injection of the antibody significantly increased the number of ECs and the mRNA levels of the EC marker CD31 and antiapoptotic Bcl2 genes compared to injection of control IgG isotype antibodies in melanoma-bearing mice." (PMID 40419762, 2025). "Cordycepin’s targeted mechanisms, such as caspase pathway activation and Bcl-2 suppression, show particular efficacy against aggressive skin cancers such as melanoma, while its antioxidant and hydration-supporting functions contribute to UV protection and improved skin resilience." (PMID 39852004, 2025). "Interaction between Nur77 and Bcl-2, which leads to the mitochondrial localization of Nur77, affects the apoptosis of tumor cells 28, 29, which is consistent with the results of this study on melanoma." (PMID 39744474, 2025). "Bromodomain PHD finger transcription factor (BPTF) promotes melanoma development by regulating B-cell lymphoma-2 (BCL2) anti-apoptosis, influencing melanocyte stem cell differentiation, and affecting melanoma proliferation via extracellular signal-regulated kinases regulation." (PMID 41479783, 2025). "In vitro, RGD-Lip-SHK could obviously inhibit multiplication, migration and invasion, and promote apoptosis by downregulating the levels of Bcl-2 and upregulating the levels of Bax in melanoma cells." (PMID 40496618, 2025). "Therefore, nucleation of Nur77 and its binding to Bcl-2 are potential mechanisms by which LNT promotes melanoma cell apoptosis." (PMID 39744474, 2025). "The limitations of this study include not testing BCL2 inhibitors in GCMN-associated melanoma and not evaluating the development of malignancies in the mouse models." (PMID 40374605, 2025). "Further experiments were conducted to determine whether LNT exerts anti-melanoma effects by regulating the interaction between Nur77 and Bcl-2." (PMID 39744474, 2025). "This is consistent with previous studies showing that the co-inhibition of Mcl-1 and other anti-apoptotic proteins, such as Bcl-xL, can significantly induce apoptosis and cell death of melanoma cell lines or sensitize glioma stem cells to other Bcl-2 inhibitors." (PMID 40707448, 2025). "pAKTS473 localizes to the melanoma cell mitochondria where it increases OXPHOS via BCL-2." (PMID 40280124, 2025). "In melanoma stem cells, miR-181a induces apoptosis by directly targeting Bcl-2." (PMID 39851559, 2025).
melanoma (continued). "In vitro, compared with non -targeted liposomes (Lip-SHK), RGD-Lip-SHK was more efficiently taken up, had higher cytotoxicity, was better targeted to inhibit cell growth, migration, and invasion, and boost cell apoptosis by regulating the expression of Bcl-2 and Bax proteins in melanoma cells." (PMID 40496618, 2025). "Therefore, orphan nuclear receptor Nur77 is poorly expression and exhibits obvious nucleation and co-localization with Bcl-2 outside the nucleus in melanoma." (PMID 39744474, 2025). "As Hippo pathway is well-known to be linked to alterations of extracellular matrix (ECM) rigidity, we investigated whether Bcl-2 affects the response of melanoma cells to different stiffness conditions and whether YAP mediates this response." (PMID 38755629, 2024). "Thus, we investigated the effects of ABT-737 and ABT-263, which target Bcl-2, Bcl-xL and Bcl-w as well as the Bcl-2-selective ABT-199 and the Mcl-1-selective S63845, in a panel of four BRAF-mutated and BRAF-WT melanoma cell lines." (PMID 38542429, 2024). "Moreover, YAP overexpression promotes anoikis resistance in melanoma cells and metastasis in in vivo experiments, through the expressions of downstream genes Bcl-2 and Mcl-1." (PMID 38755629, 2024). "Interestingly, we found that YAP silencing abolished the ability of Bcl-2 to increase cell migration and to promote cell proliferation of melanoma cells on higher stiffness condition of culture, resembling stiffer environment found in solid tumours." (PMID 38755629, 2024). "Moreover, oleocanthal downregulates the expression of antiapoptotic protein such as Bcl-xL, Mcl-1, Bcl-2, survivin in melanoma and hepatocarcinoma cells." (PMID 39203892, 2024). "PAF can inhibit apoptosis in melanoma cells by modulating the expression of anti-apoptotic proteins such as Bcl-2 and Bcl-xL, and by suppressing the activation of pro-apoptotic proteins such as caspases, contributing to the survival of melanoma cells and promoting tumor growth." (PMID 38791873, 2024). "Indeed, significant expression of both Bcl-2, Bcl-xL, Mcl-1, and Bcl-w is characteristic in melanoma cell lines." (PMID 38542429, 2024). "We validated these results in human melanoma M14 clone stably overexpressing Bcl-2." (PMID 38755629, 2024). "A previous study focused on the relationship between the phosphorylation of Bcl-2 at Thr56 and leucine-rich repeat kinase 2 (LRRK2), a relationship that may be associated with Parkinson’s disease and melanoma." (PMID 38186578, 2023). "Moreover, in melanoma cells, the Bax/Bcl-2 ratio < 1.00 is considered for resistant cells since the Bax/Bcl-2 ratio is >1.00 for sensitivity." (PMID 36613399, 2023). "Systemic administration of the antisense oligonucleotide (ASO) targeting BCL2, augmerosen, downregulated the target BCL2 protein in metastatic cancer and, combined with standard anticancer therapy, helped resensitize patients with resistant melanoma." (PMID 36678835, 2023). "Quantitative real-time polymerase chain reaction (RT-qPCR) analysis revealed that the triterpene-GNP conjugate treated A375 melanoma cells had a fold change increase in Bcl-2-associated X protein (BAX) expression and a fold change decrease in B-cell lymphoma 2 (Bcl-2) expression." (PMID 36615613, 2023). "In melanoma cells, enhanced caspase-3 activation and mitochondrial activation have been reported in response to combinations of S63845 or TW-37 (targeting Mcl-1, Bcl-xL and Bcl-2) with BRAF inhibitors (vemurafenib or encorafenib)." (PMID 36902392, 2023).
melanoma (continued). "Similarly, the expression of anti-apoptotic factor BCL-2 was significantly higher in the LNM cell line compared to primary stage melanoma MelJuSo (~26 times higher), although it registered a significant decrease in VMM1 (p < 0.0001)." (PMID 37047539, 2023). "Two models were obtained to predict metastasis (including “all patients” or only patients “at early stages of melanoma”), and a series of attributes were seen to predict the progression of metastasis: Breslow thickness, infiltrating BCL-2 expressing lymphocytes, and IL-4 and IL-6 serum levels." (PMID 37046835, 2023). "Considering that ornidazole also significantly decreased both mRNA and protein expression level of Gli1 (P < 0.001), we believe that apoptosis induced by ornidazole in the melanoma tumor tissue might be partly mediated by Gli1/Bcl2/Bax-axis." (PMID 36325671, 2022). "In addition to death ligands, melanoma TEVs can eliminate CD4+ T cells by directly targeting mitochondrial apoptosis regulator Bcl-2 through miR-690." (PMID 35454774, 2022). "Hence, the ONC-related downregulation of both STAT3 and Bcl2 can partially explain either the apoptosis induction or the reduction in colony formation found in soft agar with these two melanoma cell lines." (PMID 35742999, 2022). "These cancer cells included the histiocytic lymphoma U-937, the acute promyelocytic leukemia HL-60, the acute lymphoblastic leukemia MOLT-3, the pre-B NALM-6, the cell line over-expressing the human Bcl-2 protein (U-937/Bcl-2), and the melanoma SK-MEL-1 cell line." (PMID 36555165, 2022). "Further studies indicated apoptotic activity as revealed by the morphological changes in melanoma cells and supported by Western blot results that showed the downregulation of the anti-apoptotic Bcl-2 expression combined with the upregulation of the pro-apoptotic Bax." (PMID 36355533, 2022). "For RT‐PCR analyses, we chose melanophore marker genes pmel and mitf, neural crest markers sox10 and slug that can be reactivated in invasive melanomas, melanoma‐enriched genes bcl2 and axl, and cdh1 (E‐cadherin gene), of which expression was decreased in invasive melanomas." (PMID 35981147, 2022). "The BCL-2 expression in melanoma cells was reduced dramatically after 48 h of treatment." (PMID 35806253, 2022). "Additionally, LUT has been reported to promote apoptosis in a variety of tumor cells, including ovarian teratomas and melanomas, by decreasing Bcl-2 expression, increasing Bax expression, and inhibiting the PI3K/Akt signaling pathway." (PMID 36172186, 2022). "Clinically, a trend towards higher BCL2 mRNA expression in the BRAFi-resistant samples compared with pretreatment samples was observed by analyzing a published cohort of BRAFi-treated melanoma patients." (PMID 36202798, 2022). "However, there is also evidence that TEVs are taken up by melanoma and bladder cancer cells inhibiting apoptosis and favoring cell proliferation by targeting mitochondria through the regulation of the Bax/Bcl-2 signaling pathway." (PMID 35454774, 2022). "Furthermore, the expression levels of genes such as PTEN, cAMP, and BCL2 were generally decreased in melanoma cells." (PMID 35893303, 2022). "Next, we evaluated whether Bcl2L10was able to affect the activity of matrix metalloproteinases MMP2 and MMP9,which we previously demonstrated to be modulated by Bcl-2 and Bcl-xL in melanoma." (PMID 36046354, 2022). "Data shows that Citrullus colocynthis fruit extract has an anticancer effect on the human melanoma cell line (A375) by increasing the expression of Bax and Bcl2 andthis could be because of the phytochemicals present in it." (PMID 36518144, 2022).
melanoma (continued). "In the quickly proliferating melanoma A375 cell line, the expression levels of apoptotic protein BCL-2 and invasion-related MMP9 were significantly increased, while KYNU could promote the increased expression of MMP9 and AMPK." (PMID 35893303, 2022). "Similarly, high Bcl-2 levels have been detected in a variety of tumor types, including small cell lung, melanoma, breast, prostate, colorectal, and bladder cancers, and especially in human lymphoid malignancies." (PMID 34181356, 2021). "Furthermore the role of MITF in the regulation of the BCL2 gene activity has already been studied in melanoma cells." (PMID 34289891, 2021). "LHFPL3-AS1 via the miR-181a-5p/BCL-2 pathway could participate in tumorigenesis of melanoma stem cells." (PMID 34368145, 2021). "Small interfering RNA (siRNA)-mediated gene therapy could be a promising strategy to inhibit the expression of Bcl-2 in melanoma." (PMID 34064748, 2021). "As an antiapoptotic factor, BCL2 can increase the antiapoptotic ability of melanoma cells." (PMID 33746605, 2021). "Furthermore, cleaved caspase 3 in WM-3246 cells treated with the three-drug combination but not with sirolimus alone, validating the induction of apoptosis by co-inhibition of BCL2 and MCL1 in sirolimus-sensitized NF1/PTEN-deficient human melanoma cells." (PMID 34331013, 2021). "An earlier study revealed that knockdown of Bcl-2 in TRAIL-resistant melanoma cells could make these cells sensitive to TRAIL although the effect was not as potent as that of XIAP knockdown." (PMID 34299249, 2021). "Another study found that IGF1 could induce resistance to TRAIL in melanoma cells by upregulating Bcl-2, Bcl-xL and survivin." (PMID 34299249, 2021). "Several studies highlighted the idea that overexpression of Bcl-2 could be responsible for the chemoresistance of melanoma." (PMID 34064748, 2021). "We found that reduction of Olig2 in melanoma cells inhibited the expression of Bcl-2." (PMID 33833342, 2021). "To confirm whether the constructed Salmonella induces cell death through the apoptosis pathway in melanoma cells, we investigated the expression levels of the anti-apoptotic protein Bcl-2 in infected melanoma cells." (PMID 34835533, 2021). "This capability to study melanoma progression may be useful as prior evidence suggests that MCC cells express Bcl-2 at a higher level relative to normal Merkel cells in fetal and adult tissue." (PMID 33478104, 2021). "Considering that higher BCL2 levels are associated with sensitivity to ABT-199 in other cancers, these data provide a rationale for testing the efficacy of BCL2 inhibitors, such as ABT-199 (venetoclax), in patients with BRAF-WT melanomas." (PMID 32764384, 2020). "Finally, in tumor specimens from patients with melanoma, high bcl-2 expression correlated with increased infiltration of M2-polarized CD163+ macrophages, hence supporting the clinical relevance of the crosstalk between tumor cells and microenvironment." (PMID 32269145, 2020). "Moreover, this compound induced PARP cleavage and increased BAX expression, whereas BCL2 expression was downregulated after lj-1-59 treatment in different melanoma cell lines." (PMID 32021565, 2020). "Finally, in tumor specimens from patients with melanoma, high bcl-2 expression correlated with increased infiltration of M2-polarized CD163+ TAM, hence supporting the clinical relevance of tumor/microenvironment crosstalk." (PMID 32269145, 2020). "In this study, the findings revealed that LHFPL3-AS1-long, one of two LHFPL3-AS1 isoforms, was required for maintaining the stemness of melanoma stem cells via directly interacting with miR-181 to inhibit the mRNA degradation of its target gene Bcl-2 and apoptosis of melanoma stem cells." (PMID 33149126, 2020).